MPO (myeloperoxidase)
Diseases named in the same sentence as MPO in open-access papers (continued):
Sharing a sentence is not in itself a finding about the gene and the disease.
atherosclerosis (continued). "Increasing evidence has suggested potential links between MPO and the development of disease such as ischemia, atherosclerosis, and acute myeloid leukemia." (PMID 23593274, 2013). "It is important to keep in mind that HOCl is the most abundant product of MPO in vivo, and traces of HOCl-modified epitopes have been found in acute and chronic vascular inflammatory diseases such as atherosclerosis." (PMID 23983406, 2013). "Many studies have demonstrated that neutrophils play a major role in atherosclerosis and plaque instability through various mediators such as neutrophil gelatinase-associated lipocalin (NGAL), neutrophil-elastase, myeloperoxidase, defensins and cathelicidin." (PMID 24070055, 2013). "MPO is currently considered as one of major mediators in the genesis and development of atherosclerosis." (PMID 23451244, 2013). "MPO mediates the oxidation of proteins, lipids and DNA by generating potent hypochlorous acid (HOCl), a key mediator in the genesis of atherosclerosis." (PMID 23451244, 2013). "All these issues show that the investigations of MPO-dependent LDL oxidation are of importance to better understand the inflammatory context of atherosclerosis." (PMID 23983406, 2013). "HDL has been proposed to lose its cardio-protective effects in subjects with atherosclerosis, which involves oxidative damage by MPO." (PMID 23251382, 2012). "Here we demonstrate that a small molecule approach towards MPO inhibition is feasible and effective in reducing atherosclerosis and improving vascular function via attenuation of inflammation, oxidative stress and enhancement of cholesterol efflux." (PMID 23251382, 2012). "Presence of luminal NETs and role of MPO/H2O2/Cl– system in generation of modified LDL contributes to early stage of atherosclerosis." (PMID 23110185, 2012). "Taken together with a reduction in IL-6, these results demonstrate a beneficial role of chronic MPO inhibition on inflammation in atherosclerosis." (PMID 23251382, 2012). "Since hypercholesterolemia is associated with atherosclerosis and inflammation, we tested whether MPO serum levels were up-regulated in Familial Hypercholesterolemia (FH) and whether acute reduction of total cholesterol (TC) would also reduce MPO concentration." (PMID 22014237, 2011). "Under many pathological conditions such as atherosclerosis, endometriosis, and cancer, where MPO has been known to play a role, there have been reports of significant free iron accumulation." (PMID 22132121, 2011). "Moreover, the antioxidant property of QRC in atherosclerosis is correlated to the myeloperoxidase (MPO)/H2O2 system." (PMID 41228388, 2025). "Myeloperoxidase (MPO) is an oxidase that is related to the pathogenesis of atherosclerosis." (PMID 40421013, 2025). "Considering the conflicting role of MPO in atherosclerosis, perhaps there are more unknown roles and functions of MPO that we are yet to unravel." (PMID 39456241, 2024). "Animal studies have provided insights into the role of MPO in experimental atherosclerosis." (PMID 39061857, 2024). "Therefore, the development of inhibitors capable of targeting both MPO and peroxidasin represents a potentially promising avenue of investigation with respect to effectively targeting peroxidase-mediated pathology in atherosclerosis and MI." (PMID 39061857, 2024). "The levels of neutrophil-associated plasma proteins, such as MPO and matrix metalloproteinase 9 (MMP-9), could predict the risk of cardiovascular events related to the severity of atherosclerosis." (PMID 37569455, 2023). "The role of MPO in atherosclerosis can be suggested by the MPO catalysed reactions, with pro-atherogenic effects, transforming MPO and its inflammatory pathways into potential therapeutic targets for the prophylaxis of atherosclerosis." (PMID 38137807, 2023).
atherosclerosis (continued). "MPO contributes to the pathophysiology of diverse diseases such as rheumatoid arthritis, atherosclerosis, pulmonary fibrosis, renal glomerular injury, multiple sclerosis, Huntington’s disease, Alzheimer’s disease, Parkinson’s disease, liver diseases, diabetes, obesity, and cancer." (PMID 36768971, 2023). "In addition to its contribution to atherogenesis, MPO is abundant in unstable atheroma and promotes plaque erosion and rupture in mouse models of atherosclerosis." (PMID 36982778, 2023). "Additionally, new biomarkers of atherosclerosis (IL-6, MPO, TNF-alpha) will be measured every 6 months." (PMID 37590267, 2023). "Thus, the increased level or activity of MPO is a marker as well as a mediator involved in the pathophysiology of atherosclerosis." (PMID 36404308, 2022). "The uncontrolled production of MPO promotes inflammation, oxidative stress and atherosclerosis." (PMID 36404308, 2022). "Our previous studies indicated that Xiongshao capsule containing tetramethylpyrazine and paeoniflorin, which could reduce the serum TC, FC, and myeloperoxidase (MPO) levels in aorta cells of AS rabbits, prevented atherosclerosis." (PMID 36387364, 2022). "Free radical formation may be the cause of cellular dysfunction and the development of diseases such as atherosclerosis, rheumatoid arthritis, asthma and other diseases in which intensive MPO-dependent oxidant generation (including HOCl) is observed." (PMID 36142645, 2022). "The role of myeloperoxidase (MPO) in atherosclerosis has been investigated for several decades." (PMID 35624738, 2022). "In vivo, ApoA-I may undergo oxidation in the oxidative environments of plaques or from myeloperoxidase, an enzyme involved in atherosclerosis, leading to amyloid fibril formation." (PMID 35955915, 2022). "On the other hand, overexpression of human MPO transgene in macrophages increased atherosclerosis in mice with normal renal function, suggesting that excess macrophage MPO could worsen atherosclerosis." (PMID 33234591, 2021). "In conclusion, bone marrow MPO deficiency decreased atherosclerosis in a CKD mouse model without changes in body weight, renal function, hypercholesterolemia, or blood pressure." (PMID 33234591, 2021). "For instance, some proteins related to atherosclerosis were down-regulated in SF, such as ARG2, CD14, CD44, engulfment, and cell motility protein 1 (ELMO1), neutrophil gelatinase-associated lipocalin (LCN2), MPO, S100A8, or S100A9." (PMID 34572333, 2021). "Alternatively, non-MPO-derived inflammation might be a more critical driver of endothelial dysfunction in CKD atherosclerosis." (PMID 33234591, 2021). "Gd based MPO sensor was designed to detect inflammation in a rabbit model of atherosclerosis." (PMID 34867370, 2021). "The creation of bone marrow MPO deficiency required exposing the CKD mice to whole-body irradiation, which could have independent effects on atherosclerosis and vascular dysfunction." (PMID 33234591, 2021). "Deterioration of lipid control might accelerate the development of atherosclerosis in MPO-AAV patients." (PMID 33481903, 2021). "Similarly, myeloperoxidase (MPO), a heme protein overexpressed in human atherosclerosis lesions, can damage HDL-C particles." (PMID 33916032, 2021). "Moreover, it was suggested that myeloperoxidase (MPO) played a key role in inflammation as well as oxidative stress, and is involved in the onset and development of atherosclerosis." (PMID 34611229, 2021). "The CKD mice with bone marrow MPO deletion had decreased atherosclerosis despite a lack of differences in traditional risk factors for atherosclerosis." (PMID 33234591, 2021). "Given the associative evidence linking MPO, atherosclerosis, and vascular responses, we assessed the cholinergic responsiveness of mouse aortic rings in mice with and without bone-marrow-derived MPO." (PMID 33234591, 2021). "High levels of MPO have been detected during the progression of atherosclerosis." (PMID 33916032, 2021).
atherosclerosis (continued). "We deleted bone marrow MPO on the atherosclerosis-prone CKD mouse model." (PMID 33234591, 2021). "Considerable evidence supports a role for MPO in the pathogenesis of atherosclerosis." (PMID 31959784, 2020). "Thus, this study aimed to evaluate the plasma MPO and ANGPTL6 levels in both obese and T2D patients and to assess their association with the biochemical markers of obesity, inflammation, and atherosclerosis." (PMID 32277104, 2020). "In this way, HOSCN may skew the oxidative profile of MPO, thus reducing oxidative injury of the arterial wall in atherosclerosis." (PMID 32899436, 2020). "Moreover, the level of MPO enzyme is also discussed as being a prompt indicator of endothelial dysfunction, inflammation, atherosclerosis, and oxidative stress." (PMID 32899838, 2020). "Biomarkers of oxidative stress, such as MMPs, myeloperoxidase (MPO), oxLDL, or Nox could emerge as useful molecules to identify subclinical atherosclerosis once accurate screening methods become available." (PMID 31354915, 2019). "In addition to its role in atherosclerosis, MPO also drives the inflammatory process that occurs after cardiac injury, such as in myocardial infarct." (PMID 30889221, 2019). "In a cross-sectional study, the Atherosclerosis Risk in Communities (ARIC) Study found monocyte MPO (mMPO) to be negatively, not positively, associated with the prevalence of peripheral artery disease (PAD)." (PMID 30300402, 2018). "Oxidative modification of HDL particles by MPO may contribute to the development of progression atherosclerosis in stable coronary artery disease." (PMID 29618370, 2018). "A heme-containing peroxidase, myeloperoxidase (MPO), is expressed in monocytes and neutrophils and may contribute to lipid oxidation in atherosclerosis through ROS." (PMID 30347819, 2018). "Previous studies have hypothesized that the number of PMNs in circulation, and the amount of PMN-produced elastase and myeloperoxidase, correlate with both atherosclerosis and myocardial infarction." (PMID 28420383, 2017). "Given that myeloperoxidase is highly implicated in atherogenesis, supplementation with a TRF could therefore prevent the development of atherosclerosis." (PMID 28880217, 2017). "Furthermore, myeloperoxidase (MPO) and paraoxonase 1 (PON1) are HDL-associated proteins that bind to HDL and are mechanistically linked to inflammation, oxidative stress, and atherosclerosis." (PMID 28611100, 2017). "Based on this reported evidence, in combination with the present study, the combination of VAP-1/SSAO and MPO could synergistically increase production of M2FA at atherosclerosis sites." (PMID 28883613, 2017). "The detection of increased levels of the HOCl-specific marker, 3-chlorotyrosine, in LDL isolated from human lesions, together with evidence for the presence of MPO-LDL complexes in the circulation of patients with atherosclerosis, support MPO as a pathway to LDL modification in vivo." (PMID 27997605, 2016). "On the other hand, once released into the bloodstream MPO may disseminate to remote tissues thereby accelerating generalized atherosclerosis." (PMID 27127544, 2016). "Previous studies have hypothesized that the number of PMNs in circulation, and the amount of PMN-produced elastase and myeloperoxidase (MPO) correlate with atherosclerosis." (PMID 27430968, 2016). "In addition, lipid oxidation/chlorination by the MPO/HOCl system is suggested to contribute to the pathogenesis of atherosclerosis and SLE." (PMID 26904693, 2016). "The presence of G-allele rather than A-allele increases the expression of MPO, which can be the reason of higher enzyme activity in atherosclerosis as well as several malignant, degenerative, and inflammatory diseases." (PMID 27127544, 2016). "In a future study, we will examine whether there are distinct roles for VPO1 and MPO in pathogenesis of atherosclerosis." (PMID 27167346, 2016).
atherosclerosis (continued). "However, macrophages exposed to HOSCN-modified LDL accumulate cholesterol to a lesser extent compared to HOCl-modified LDL, and human MPO transgenic atherosclerosis-prone mice supplemented with SCN- show a reduced extent of lesion formation." (PMID 27997605, 2016). "MPO plays an important role in atherosclerosis via oxidation of proteins and lipids." (PMID 27167346, 2016). "More often, myeloperoxidase may contribute to the generation of dysfunctional HDL with impaired ABCA1 efflux capacity in humans with atherosclerosis." (PMID 25949827, 2015). "MPO and its oxidant products, nitrotyrosine, and chlorotyrosine have been identified in atherosclerotic plaque and at the site of plaque rupture and play important role in the genesis of atherosclerosis." (PMID 25949827, 2015). "MPO and the reactive intermediates it generates have been identified in atherosclerotic lesions and MPO may thus contribute to the oxidation of low density lipoproteins (LDL) that ultimately leads to atherosclerosis." (PMID 25698971, 2015). "ADMA together with related markers of oxidative stress like myeloperoxidase could potentiate development of atherosclerosis." (PMID 26778898, 2015). "MPO has been reported to promote atherosclerosis via inducing oxidative stress in animal models." (PMID 25993296, 2015). "The study by Zhang demonstrated that MPO was not necessary to induce an experimental atherosclerosis model in MPO-deficiency-induced mice." (PMID 26719776, 2015). "Furthermore, these data strengthen the model of the MPO-dependent oxidation of LDL in the circulation as a contributive mechanism of atherosclerosis." (PMID 23983406, 2013). "Revealed in this study the ability of MPO to increase the activity of platelets may serve as an additional mechanism for the involvement of MPO in the development of atherosclerosis." (PMID 24143278, 2013). "However, the effect of synthetic myeloperoxidase inhibitors on atherosclerosis has been insufficiently studied." (PMID 23251382, 2012). "Moreover, patients with CSA had substantial atherosclerosis of coronary arteries, but circulating neutrophils had a relatively normal MPO content." (PMID 22761804, 2012). "In addition, extremely low MPO activity was found in the samples obtained from control group, and the MPO activity in atherosclerosis group showed significantly higher in comparison to the probucol group." (PMID 22078494, 2011). "Recently it has been suggested that myeloperoxidase (MPO), a “heme” protein derived from leukocytes, plays an important role in leukocyte-mediated vascular injury responses in inflammatory vascular diseases such as diabetic vasculopathy and atherosclerosis." (PMID 21234421, 2010). "MPO has emerged as a potential participant in the promotion of atherosclerosis." (PMID 19549340, 2009). "Thus, pharmacotherapeutic MPO inhibition in humans is possible and might be tested in a translational approach to prove beneficial effects on endothelial function and atherosclerosis development in patients with obesity." (PMID 40252642, 2025). "Additionally, research has indicated that the release of NETs by neutrophils can worsen vascular endothelial injury by generating cytotoxic proteases (e.g., histones, elastase, myeloperoxidase MPO), and pro-inflammatory mediators, ultimately contributing to the development of atherosclerosis." (PMID 40809841, 2025). "Lipoprotein Oxidation: MPO is implicated as a principal source of oxidants that modify and convert LDL into a high-uptake form that is recognised by macrophage scavenger receptors, leading to macrophage foam cells that play a central role in driving the progression of atherosclerosis." (PMID 39061857, 2024). "In addition, acetaminophen can inhibit other peroxidase including myeloperoxidase, reduce the formation of halogenated oxidants (such as hypochlorite and hypobromous acid), and may slow down the development of atherosclerosis and other diseases." (PMID 39193324, 2024).
atherosclerosis (continued). "The oxidative stress and resulting proinflammatory milieu observed in conditions such as atherosclerosis, rheumatoid arthritis, kidney disease, inflammatory bowel disease, and neurodegenerative disorders have commonly been attributed to the activity or overactivity of myeloperoxidase." (PMID 36674761, 2023). "MPO could be released extracellularly; augmented serum levels of MPO have been described in chronic inflammatory conditions typical of age-related diseases such as atherosclerosis, neurodegenerative conditions, and some cancers." (PMID 36829808, 2023). "Interestingly, expression of MPO by macrophages is increased at the later stages of atherosclerosis contrary to the initial atherosclerotic lesions (i.e., fatty streaks) in a process controlled by proinflammatory mediators such as granulocyte macrophage colony-stimulating factor (GM-CSF)." (PMID 37895374, 2023). "Although complete lack of MPO can increase the risk of infection, excess MPO-derived oxidative products are associated with multiple inflammatory disease states including obesity, insulin resistance, atherosclerosis, and heart failure." (PMID 38004170, 2023). "Thus, MPO is an important factor in the development and progression of atherosclerosis." (PMID 37405052, 2023). "Further research is needed to understand the underlying mechanisms involved in the dual role of Mox-LDLs and MPO in human atherosclerosis plaques and inflammation, but the production or liberation of RvD1 by Mox-LDLs-stimulated endothelial cells may be a reasonable starting point." (PMID 35624738, 2022). "MPO expression and evidence of MPO activity are present in the proximity of macrophages in atherosclerotic lesions from patients; however, a causal role of macrophage MPO in atherosclerosis has not been established." (PMID 33234591, 2021). "However, the oxidant enzyme MPO was also found to be increased in the current study, which could lead to an increase in lipid peroxidation as MPO is known to be involved in lipid peroxidation, plaque formation and atherosclerosis in vessels." (PMID 31072373, 2019). "The results also strongly suggest that atherosclerosis lesions possess an environment conducive for M2FA production under lipid peroxidation because of likely higher steady-state levels of endogenous FA derived from an MPO-mediated reaction and physiological FA metabolism." (PMID 28883613, 2017). "In addition, MPO can also promote inflammation and atherosclerosis." (PMID 29149031, 2017). "Because MPO is distributed in inflammatory cells with approximately 5% of dry weight of the cell and has stronger peroxidase activity, we hypothesize that MPO may play a dominant role in the acute stage of atherosclerosis." (PMID 23451244, 2013). "This interaction is critical, as MPO is released from activated leukocytes during inflammation, linking HDL dysfunction to the inflammatory milieu characteristic of atherosclerosis." (PMID 39941147, 2025). "Taken together, MPO is considered to contribute to HDL dysfunction, which participates in the pathologic process of atherosclerosis." (PMID 38275657, 2024). "This is synonymous with the canonical idea that MPO is detrimental to the progression of CAD and atherosclerosis." (PMID 39456241, 2024). "A significant downregulation was also seen for myeloperoxidase (MPO), azurocidin (AZU) and proteinase 3 (PRTN3), which are all atherosclerosis biomarkers." (PMID 38715599, 2024). "Several studies have shown a strong correlation between MPO and cardiovasculardisease (CVD) including acute coronary syndrome, atherosclerosis, hypertension,and stroke." (PMID 39077419, 2023). "The inhibition of MPO has been proposed as a strategy for resolution of inflammation in the context of IBD, atherosclerosis, neurodegenerative disorders, cancer, and infections." (PMID 36293108, 2022).